ADRA2C (adrenoceptor alpha 2C)
Description:
Alpha-2 adrenergic receptors are G protein-coupled receptors for catecholamines that activate the G(i/o) protein pathway, thereby promoting adenylyl cyclase inhibition, ERK1/2 stimulation, and voltage-gated calcium channels suppression. Control a variety of physiological processes, such as regulation of blood pressure, lipolysis and insulin release. ADRA2A and ADRA2C mediates the presynaptic feedback inhibition of neurotransmitter release from noradrenergic nerve terminals in sympathetic and central nervous systems. ADRA2A inhibits transmitter release at high stimulation frequencies, whereas ADRA2C modulates neurotransmission at lower levels of nerve activity (By similarity). The rank order of potency for physiological agonists of ADRA2C is epinephrine > norepinephrine > dopamine.
Synonyms: ADRA2L2; ADRA2RL2; ADRARL2; ALPHA2CAR
Tractability: Small molecule: an approved drug acts on it; a structure with a bound ligand is known; a high-quality ligand is known; it belongs to a druggable protein family. Antibody: its Gene Ontology location is reachable by antibodies, with high confidence; UniProt places it where antibodies can reach, with medium confidence; UniProt predicts a signal peptide or a membrane-spanning region. PROTAC: a small molecule that binds it is known. Other modalities: an approved drug acts on it.
Target class: Small molecule receptor (family A GPCR); Adrenergic receptor; Monoamine receptor; Membrane receptor; Family A G protein-coupled receptor
Chemical probes: JP1302
Safety:
Unwanted effects reported when the protein is acted on. In parentheses: how it was acted on, where the effect was seen, and who reports it.
cardiac ischemia (activation; cardiovascular system, central nervous system; source: Urban et al. (2012))
hypertension (activation; cardiovascular system, central nervous system; source: Urban et al. (2012))
locomotion (activation; cardiovascular system, central nervous system; source: Urban et al. (2012))
startle reflex (activation; cardiovascular system, central nervous system; source: Urban et al. (2012))
stress response (activation; cardiovascular system, central nervous system; source: Urban et al. (2012))
venous contraction (contraction of human saphenous vein) (activation; cardiovascular system, central nervous system; source: Urban et al. (2012))
Gene: Protein-coding gene on chromosome 4 (3,766,348 to 3,768,526, forward strand). Ensembl gene ENSG00000184160.
Subcellular location: Cell membrane
Pathways (Reactome):
Signal Transduction: Adrenoceptors; G alpha (i) signalling events; G alpha (z) signalling events
Hemostasis: Adrenaline signalling through Alpha-2 adrenergic receptor
Metabolism: Adrenaline,noradrenaline inhibits insulin secretion
Metabolism of proteins: Surfactant metabolism
Gene Ontology:
Molecular function: alpha-2A adrenergic receptor binding; alpha2-adrenergic receptor activity; epinephrine binding; protein binding; protein heterodimerization activity; protein homodimerization activity; adrenergic receptor activity; G protein-coupled receptor activity
Biological process: adrenergic receptor signaling pathway; epidermal growth factor receptor signaling pathway; G protein-coupled receptor signaling pathway; negative regulation of norepinephrine secretion; positive regulation of MAPK cascade; positive regulation of neuron differentiation; positive regulation of phosphatidylinositol 3-kinase/protein kinase B signal transduction; adenylate cyclase-inhibiting adrenergic receptor signaling pathway; cell-cell signaling; negative regulation of epinephrine secretion; negative regulation of insulin secretion; platelet activation; regulation of smooth muscle contraction; regulation of vasoconstriction
Cellular component: cytoplasm; plasma membrane; endosome; membrane
Genetic constraint (gnomAD): Loss-of-function variants: 4 observed, 8.19 expected, observed/expected ratio (o/e) 0.49, 90% interval 0.24 to 1.12. That is too few expected variants to judge how well the gene tolerates losing a copy. Missense variants: 582 observed, 613.44 expected, observed/expected ratio (o/e) 0.95, 90% interval 0.89 to 1.02. Synonymous variants: 359 observed, 287.69 expected, observed/expected ratio (o/e) 1.25, 90% interval 1.14 to 1.36.
Homologues: Orthologues: macaque ADRA2C (98% identical), dog ADRA2C (95% identical), pig ADRA2C (94% identical), rat Adra2c (93% identical), mouse Adra2c (93% identical), chimpanzee ADRA2C (74% identical), tropical clawed frog adra2c (63% identical), zebrafish adra2c (58% identical), Caenorhabditis elegans ser-5 (21% identical). Paralogues in human: ADRA2A (51% identical), ADRA2B (48% identical), DRD2 (28% identical), ADRA1B (27% identical), ADRA1A (26% identical), ADRA1D (26% identical), ADRB1 (24% identical), ADRB3 (23% identical), ADRB2 (22% identical), GPR101 (15% identical), OR5T1 (13% identical), OR5T2 (13% identical), and 6 more.
Diseases named in the same sentence as ADRA2C in open-access papers:
ADRA2C is named in the same sentence as 45 diseases in open-access papers, as found by Europe PMC text mining. Sharing a sentence is not in itself a finding about the gene and the disease. The quoted sentences say what the papers report.
schizophrenia (5 papers, 2015 to 2023). A major psychotic disorder characterized by abnormalities in the perception or expression of reality. "In conclusion, epigenetic predisposition differentially modulated ADRA2A and ADRA2C mRNA expression in DLPFC of schizophrenia subjects." (PMID 34930904, 2021). "ADRA2A mRNA expression was selectively upregulated in AP-treated schizophrenia subjects (+93%) whereas ADRA2C mRNA expression was upregulated in all schizophrenia subjects (+53%) regardless of antipsychotic treatment." (PMID 34930904, 2021). "In schizophrenia subjects ADRA2C mRNA expression was significantly higher than in matched controls (Δ = +53%, n = 17, p = 0.016)." (PMID 34930904, 2021). "The results show specific histone PTMs at ADRA2A and ADRA2C promoters in schizophrenia with selective mechanisms in AP-free and AP-treated subjects." (PMID 34930904, 2021). "The study of histone PTMs at ADRA2C promoter region in schizophrenia subjects showed a significant increase of H3K27me3 (Δ = +52%, p = 0.046), H3K9ac (Δ = +63%, p = 0.007) and H4K5ac (Δ = +55%, p = 0.027)." (PMID 34930904, 2021). "In this study, we observed a differential ADRA2A and ADRA2C mRNA expression in DLPFC of schizophrenia subjects." (PMID 34930904, 2021). "The present study aimed to assess the mRNA expression of ADRA2A and ADRA2C in postmortem DLPFC of schizophrenia subjects." (PMID 34930904, 2021). "Considering the specific ADRA2A mRNA increase observed in AP-treated schizophrenia subjects, we aimed to evaluate the effect of acute and chronic antipsychotic treatment in rat brain cortex Adra2a and Adra2c mRNA expression." (PMID 34930904, 2021). "In summary, the current study shows ADRA2A and ADRA2C differential regulation in schizophrenia." (PMID 34930904, 2021). "However, mRNA and protein expression do not necessarily need to be regulated in parallel and the increase in ADRA2C mRNA expression in schizophrenia deserves further investigation." (PMID 34930904, 2021). "ADRA2A and ADRA2C mRNA expression in schizophrenia subjects could also be influenced by the fact that most schizophrenia subjects in the study were suicide victims (13 out of 19)." (PMID 34930904, 2021). "On the other hand, increased ADRA2C mRNA expression in schizophrenia might be due to the pathophysiology of the disease or to the effect of antipsychotic treatment." (PMID 34930904, 2021). "Thus, increased ADRA2C mRNA expression in schizophrenia might be related to α2C-adrenoceptor antagonism by some atypical antipsychotic drugs." (PMID 34930904, 2021). "Thus, we aimed to evaluate if enhanced ADRA2C mRNA expression in these schizophrenia subjects could be related to suicide completion by using a cohort of 13 depressed suicide victims." (PMID 34930904, 2021). "Regarding ADRA2C epigenetic regulation, present results show that in DLPFC of schizophrenia subjects enhanced repressive H3K27me3, and permissive H3K9ac and H4K5ac coexist at ADRA2C promoter region." (PMID 34930904, 2021). "The results showed that neither ADRA2A nor ADRA2C mRNA were altered in depressed suicide victims as opposed to results in the schizophrenia cohort." (PMID 34930904, 2021). "An alternative approach would have been to study ADRA2A and ADRA2C mRNA expression in human brain of subjects treated with antipsychotic drugs but without schizophrenia diagnose." (PMID 34930904, 2021). "ADRA2A mRNA expression was selectively upregulated in AP-treated subjects, whereas ADRA2C mRNA expression was enhanced in schizophrenia subjects regardless of the presence or absence of antipsychotics in blood at the time of death." (PMID 34930904, 2021). "By contrast, ADRA2C mRNA expression was upregulated in postmortem brain of schizophrenia subjects regardless of the presence of antipsychotics in blood." (PMID 34930904, 2021). "However, ADRA2C mRNA expression was non-significantly enhanced over control values in both AP-free and AP-treated schizophrenia subjects." (PMID 34930904, 2021).
schizophrenia (continued). "The aim of this study was to evaluate ADRA2A and ADRA2C gene expression (codifying for α2-adrenoceptor subtypes), and permissive and repressive histone PTMs at gene promoter regions in the DLPFC of subjects with schizophrenia and matched controls (n = 24 pairs)." (PMID 34930904, 2021).
colorectal cancer (2 papers, 2019 to 2024). A primary or metastatic malignant neoplasm that affects the colon or rectum. "In colorectal cancer ADRA2C gene expression has been identified as a predictor of advanced clinical stage." (PMID 31391080, 2019). "Nevertheless, prior research demonstrated that ADRA2C is involved in the tumorigenesis of diverse cancer types, such as breast cancer 10 and colorectal cancer 11, suggesting that ADRA2C may be a novel biomarker for the diagnosis or treatment of cancer." (PMID 39308687, 2024).
depression (2 papers, 2021). "In order to evaluate this possibility, we analyzed ADRA2A and ADRA2C mRNA expression in suicide victims with an antemortem diagnosis of major depression." (PMID 34930904, 2021).
adrenocortical carcinoma (1 paper, 2024). "The frequency of ADRA2C alteration (2.2%) was the highest in adrenocortical carcinoma with 'mutation' as the primary type, and all adrenocortical carcinoma patients had ADRA2C mutation." (PMID 39308687, 2024). "It was revealed that a high ADRA2C expression level was associated with a favorable OS in GBM-LGG (HR= 0.53, p<0.001) and uveal melanoma (UVM) (HR= 0.34, p=0.017), while a high ADRA2C expression level was correlated with a poor OS in adrenocortical carcinoma (ACC) (HR=2.35, p=0.035)." (PMID 39308687, 2024). "Meanwhile, it was found that ADRA2C may play roles in prognosis of adrenocortical carcinoma (ACC), glioblastoma multiforme and lower grade glioma (GBM-LGG), and uveal melanoma (UVM)." (PMID 39308687, 2024).
Auditory hallucination (1 paper, 2023). Perception of sounds without auditory stimulus. "For example, ADRA2C inhibition was associated with auditory hallucination and paranoia in FAERS, on AC50 and margin measures." (PMID 37468498, 2023).
breast invasive carcinoma (1 paper, 2024). "It was revealed that the expression level of ADRA2C varied across different clinical stages in patients with breast invasive carcinoma (BRCA), esophageal adenocarcinoma (ESCA), kidney renal papillary cell carcinoma (KIRP) and lung squamous cell carcinoma (LUSC)." (PMID 39308687, 2024).
cervical squamous cell carcinoma (1 paper, 2024). A squamous cell carcinoma arising from the cervical epithelium. "Moreover, ADRA2C may be a promising diagnostic marker for cervical squamous cell carcinoma and endocervical adenocarcinoma (CESC), cholangiocarcinoma (CHOL), GBM, GBMLGG, kidney chromophobe (KICH), and KIRP." (PMID 39308687, 2024). "Meanwhile, the highest frequency in the 'deep deletion' type of ADRA2C was found in cervical squamous cell carcinoma patients." (PMID 39308687, 2024).
cholangiocarcinoma (1 paper, 2024). A carcinoma that arises from the intrahepatic biliary tree (intrahepatic cholangiocarcinoma) or from the junction, or adjacent to the junction, of the right and left hepatic ducts (hilar cholangiocarcinoma). "Compared with normal group, ADRA2C mRNA expression level was higher in cholangiocarcinoma (CHOL), colon adenocarcinoma (COAD), head and neck squamous cell carcinoma (HNSC), liver hepatocellular carcinoma (LIHC), rectum adenocarcinoma (READ) and thyroid carcinoma (THCA)." (PMID 39308687, 2024).
chronic kidney disease (1 paper, 2021). Impairment of the renal function secondary to chronic kidney damage persisting for three or more months. "It was reported that the gene coding ADRA2C is associated with beta blockers response in a group of patients troubled by chronic kidney disease." (PMID 34479477, 2021).
esophageal adenocarcinoma (1 paper, 2024). A malignant tumor with glandular differentiation arising predominantly from Barrett mucosa in the lower third of the esophagus. "The results indicated that there was a pathological stage-specific expression level of ADRA2C in BRCA, esophageal adenocarcinoma (ESCA), KIRP, and lung squamous cell carcinoma (LUSC) (p<0.05)." (PMID 39308687, 2024).
esophageal squamous cell carcinoma (1 paper, 2024). Esophageal squamous cell carcinoma (ESCC) is a type of esophageal carcinoma (EC) that can affect any part of the esophagus, but is usually located in the upper or middle third. "Moreover, a high ADRA2C expression level was associated with a favorable PFI in GBMLGG (HR=0.58, p<0.001) and UVM (HR=0.36, p=0.012), while a high ADRA2C expression level was correlated with a poor PFI in ACC (HR=2.39, p=0.009), and esophageal squamous cell carcinoma (ESCC) (HR=2.12, p=0.028)." (PMID 39308687, 2024).
glioma (1 paper, 2024). A benign or malignant brain and spinal cord tumor that arises from glial cells (astrocytes, oligodendrocytes, ependymal cells). "Finally, in vitro and in vivo experiments confirmed that the expression level of ADRA2C may be associated with glioma cell migration, apoptosis, and invasion." (PMID 39308687, 2024). "According to KEGG database and previous findings, wound healing assay was applied to assess the key apoptosis-related markers, including Bax and Bcl-2, and invasion-related protein, MMP2, for validation the anti-cancer effect and mechanism of ADRA2C drugs in glioma 33-36." (PMID 39308687, 2024). "This suggested that a lower ADRA2C expression level may promote the glioma cell apoptosis and invasion." (PMID 39308687, 2024). "The wound healing assay was performed to explore the role of ADRA2C in glioma cell migration." (PMID 39308687, 2024). "The results revealed that ADRA2C was commonly correlated with neuronal system-related pathways, especially in ACC, CESC, GBM, GBMLGG, KIRP, and lower grade glioma (LGG)." (PMID 39308687, 2024).
heart failure (1 paper, 2008). Inability of the heart to pump blood at an adequate rate to meet tissue metabolic requirements. "Given the potential synergistic effects of these polymorphisms in the ADRB1 and ADRA2C genes, two previous studies have investigated and identified epistatic interactions affecting heart failure risk and response to β-blockers in heart failure patients." (PMID 18947427, 2008).
retinoblastoma (1 paper, 2024). A malignant tumor that originates in the nuclear layer of the retina. "Besides, the single-cell sequencing data analysis indicated that ADRA2C played a role in multiple tumor development processes in GBM, retinoblastoma (RB), and UVM." (PMID 39308687, 2024). "The analysis of single-cell sequencing data indicated that ADRA2C expression level was significantly positively correlated with angiogenesis and differentiation in GBM and retinoblastoma (RB), as well as inflammation in RB and stemness in UM." (PMID 39308687, 2024).
cancer (3 papers, 2018 to 2024). A tumor composed of atypical neoplastic, often pleomorphic cells that invade other tissues. "The data from TIMER 2.0 indicated that there was a positive correlation between ADRA2C expression level and cancer-associated fibroblast in BLCA, BRCA-Basal, CESC, ESCA, HNSC, KIRP, LIHC, STAD, and THYM, as well as a negative correlation in TGCT." (PMID 39308687, 2024). "The diagnostic ability of ADRA2C in pan-cancer was evaluated through ROC curve analysis." (PMID 39308687, 2024). "Alternatively, ADRA2C emerged to be capable of discerning cancer patients from healthy subjects with notable sensitivity and specificity in CESC, CHOL, GBM, GBMLGG, KICH, KIRP." (PMID 39308687, 2024). "There is a scarcity of systematic analyses elucidating the role of ADRA2C across different types of cancer." (PMID 39308687, 2024). "In order to fully explore the correlation between ADRA2C expression and immune cell infiltration in various cancer types, immune cell infiltration analysis was conducted utilizing two sources." (PMID 39308687, 2024). "In conclusion, the role of ADRA2C in pan-cancer was systematically evaluated through multiple bioinformatics methods and preliminary experiments." (PMID 39308687, 2024). "Antagonism, for most of the selected targets (genes in purple), and agonism, for RARA, RARB, and ADRA2C (genes in red), were proposed as potential approaches for anti‐aging and anti‐cancer treatment." (PMID 37888486, 2023). "The expression level of ADRA2C in pan-cancer involving 33 cancer types was analyzed." (PMID 39308687, 2024). "However, no study has reported the correlation between ADRA2C and pan-cancer, and the function of ADRA2C in pan-cancer remains elusive." (PMID 39308687, 2024). "The ADRA2C expression level in different pathological stages in pan-cancer was analyzed." (PMID 39308687, 2024). "The correlation between ADRA2C expression level and prognosis in pan-cancer was evaluated." (PMID 39308687, 2024). "Pan-cancer analysis could be a comprehensive method to investigate the role of ADRA2C in various human cancer types." (PMID 39308687, 2024). "ADRA2C is involved in various processes of tumorigenesis and could serve as a notable target for cancer diagnosis and immunotherapy." (PMID 39308687, 2024). "Further research is necessary to authenticate the precision of the outcomes of bioinformatics analysis and to explore the molecular mechanisms involving ADRA2C in GBM and other cancer types." (PMID 39308687, 2024). "Consequently, ADRA2C may be a promising target for cancer immunotherapy." (PMID 39308687, 2024). "In addition, we found some up-regulated genes, ADRA2C, C3, and C5AR1, which were not previously reported in cancer stemness." (PMID 30420637, 2018).
tumor (2 papers, 2019 to 2024). "Taken together, all these clues demonstrated ADRA2C expression was associated with several immune cell infiltration and thus regulated the tumor microenvironment." (PMID 39308687, 2024). "For tumor tissue data from TCGA, a higher ADRA2C mRNA expression level was found in CHOL, OV, TGCT, and UCEC." (PMID 39308687, 2024). "It is possible that ADRA2C may be functionally involved in the accelerated tumour growth observed in vivo in this present study." (PMID 31391080, 2019).
ADRA2C also shares sentences with these, for which no sentence is quoted: Parkinson's (2 papers); Alzheimer disease (1); anxiety disorder (1); bladder urothelial carcinoma (1); breast carcinoma (1); cavernous hemangioma (1); colon adenocarcinoma (1); endocervical adenocarcinoma (1); glioblastoma multiforme (1); head and neck squamous cell carcinoma (1); hypotension (1); Intellectual disability (1); kidney (1); lung adenocarcinoma (1); lung squamous cell carcinoma (1); manic depression (1); mesothelioma (1); oral squamous cell carcinoma (1); pancreatic adenocarcinoma (1); Paranoia (1); pheochromocytoma and paraganglioma (1); prostate adenocarcinoma (1); psychiatric disorder (1); rectum adenocarcinoma (1); sarcoma (1); thyroid carcinoma (1); tuberous sclerosis (1); uterine corpus endometrial carcinoma (1); uveal melanoma (1).